HIF1A (hypoxia inducible factor 1 subunit alpha)
Diseases named in the same sentence as HIF1A in open-access papers (continued):
Sharing a sentence is not in itself a finding about the gene and the disease.
Cerebral ischemia (continued). "HIF-1α is a master regulator of cellular adaptation to hypoxia and has been suggested as a potent therapeutic target in cerebral ischemia." (PMID 26537366, 2015). "Changes in Hif-1a expression by the administration of either anti miR-335 or miR-335 mimic in cerebral ischemia were accompanied with the corresponding alteration of the downstream genes Angpt2, Bnip3, Mmp9, Pai1 and Vegfa." (PMID 26030758, 2015). "Hypoxia-inducible factor 1α (HIF-1α) is an important transcription factor during cerebral ischemia damage." (PMID 26715469, 2015). "Although HIF-1α has been widely known to be upregulated in rats subjected to cerebral ischemia, but the exact role of HIF-1α is still being debated." (PMID 26715469, 2015). "VEGF has been shown to play an important role in angiogenesis of cardiovascular and cerebral ischemia, which can be overexpressed by activated HIF-1α." (PMID 25905434, 2015). "These available findings not only confirm the neuroprotective effect of LRIP, but also provide new information to understand the role of HIF-1α as a novel target for the treatment of brain ischemia in future clinic practice." (PMID 26715469, 2015). "In our experimental model, LRIP exhibits significant neuroprotection in brain ischemia rats, and the molecular mechanism should involve the modulation of HIF-1α." (PMID 26715469, 2015). "The present finding revealed LRIP exhibiting a neuroprotective role was related with the inhibition of HIF-1α, a critical inflammation mediator during brain ischemia." (PMID 26715469, 2015). "In this study, we found LRIP had the neuroprotective effect in brain ischemia rats, and the possible molecular mechanism is involving in the change of HIF-1α." (PMID 26715469, 2015). "It has been shown that HIF-1α knockdown increases brain injury in a mouse model of transient focal cerebral ischemia." (PMID 24887017, 2014). "Consistent with the role of HIF-1α in STI-1 expression, double-immunofluorescence of the brain slices from rats 24 h post-cerebral ischemia showed that cells expressing HIF-1α are also expressing STI-1." (PMID 23836498, 2013). "Taken together, our data suggests that during cerebral ischemia, binding of HIF-1α to the STI-1 promoter triggers an upregulation of STI-1, which act as a self-protective mechanism to reduce brain damage." (PMID 23836498, 2013). "This dynamic regulation may partially explain the seemingly paradoxical effects of HIF‐1α/VEGF/Notch1 on the pathological processes of cerebral ischemia." (PMID 40019048, 2025). "Under extreme conditions of cerebral ischemia‐reperfusion, HIF‐1α is pathologically overexpressed in tissue cells, resulting in abnormal elevations of VEGF and Notch1, which may not be conducive to the protection of neural function." (PMID 39364701, 2024). "Past studies have shown that hypoxia-inducible factor 1-alpha (HIF1α) is an essential protein in Piezo1/calcium signaling, ferritin pendulous regulation, and cerebral ischemia, and HIF1α expression is increased in neurons and astrocytes after cerebral ischemia." (PMID 39539343, 2024). "The increase of HIF-1α protein was also observed in mice and primate brains after experimental cerebral ischemia, which might account for the early neuroprotective role of HIF-1α." (PMID 38393376, 2024). "Thus, there is every reason to believe that INI, through the IR/IRS/PI3K/AKT signaling pathway, can stimulate HIF-1α activity, facilitating the adaptation of neurons and glial cells to cerebral ischemia, although this requires further research." (PMID 36834685, 2023). "HIF-1α serves as an oxygen-dependent transcriptional activator that is upregulated during hypoxia and acts as a master regulator for hypoxia-responsive genes that provide neuroprotection following cerebral ischemia." (PMID 36979670, 2023).
Cerebral ischemia (continued). "Following activation, HIF-1α regulates the transcription and translation of several target genes that are involved in angiogenesis, glucose transport and metabolism, and cell survival following cerebral ischemia." (PMID 36979670, 2023). "It has been proved that BNIP3 overexpression can be mediated by HIF-1α in cerebral ischemia." (PMID 37101593, 2023). "The complexity of the relationship between ROS and HIF-1α in cerebral ischemia is primarily due to the various ROS species generated by the mitochondrial O2 metabolism and their properties, such as the reactivity, chemical nature, specificity, and half-life of their biological targets." (PMID 35055089, 2022). "The present study was designed to explore the effect and mechanism of NLXTD on brain angiogenesis in a rat model with cerebral ischemia-reperfusion (I/R) injury targeting the hypoxia-inducible factor-1α (HIF-1α)/vascular endothelial growth factor (VEGF) pathway." (PMID 35449809, 2022). "HIF-1α protects gene transcription by regulating the adaptive response to hypoxia and other stresses and plays a key role in the activation of endogenous substances downstream of cerebral ischemia." (PMID 35265143, 2022). "There are two phases of HIF-1a activation after cerebral ischemia." (PMID 35806000, 2022). "In addition, it was reported that HIF-1α interaction with VEGF-Notch1 can also play a very important role in regulating neurovascular regeneration after cerebral ischemia." (PMID 35035668, 2022). "In brief, the purpose of this study was to determine whether a molecular cascade involving HIF-1α, VEGF, and Notch is causally related to the regulation of angiogenesis in brain tissues by treating a rat model of cerebral ischemia with NLXTD." (PMID 35449809, 2022). "Furthermore, NOX2 and iNOS expression were reduced by impairing PI3K/protein kinase B- (AKT-) dependent NF-κB and HIF-1α activation in cerebral ischemia in mice." (PMID 35154564, 2022). "However, the mechanism of NLXTD in promoting angiogenesis after cerebral ischemia and its relationship with HIF-1a, VEGF, and Notch is still unclear." (PMID 35449809, 2022). "GHI induces a protective effect on cerebral ischemia via the PKC/HIF-1α signaling pathway, which may be a potential mechanism for GHI to alleviate CIRI." (PMID 35265143, 2022). "There are a number of pathological conditions such as cerebral ischemia, acute kidney disease, ischemic heart disease, neonatal hypoxia-ischemic brain injury, cancer, and pulmonary arterial hypertension where both HIF1α and ROS have been reported to be important players." (PMID 34596045, 2021). "Taken together, HIF-1α increases after cerebral ischemia, and its expression level is dependent on ischemic duration, which may partially explain the seemingly contradictory effects on the pathological process of stroke." (PMID 34966392, 2021). "Taken together, HIF-1a in microglia may serve as a potential therapeutic target for relieving inflammation reactions and neuronal damage after cerebral ischemia." (PMID 34966392, 2021). "Nevertheless, several studies reported opposite effects of HIF-1α in cerebral ischemia." (PMID 34336097, 2021). "Consequently, arginine inhibits inflammatory response in microglia by inhibiting HIF-1α/LDHA signaling after cerebral ischemia insult." (PMID 32321555, 2020). "To test whether the arginine/HIF-1α/LDHA pathway is neuroprotective after cerebral ischemia injury, we carried out TTC test." (PMID 32321555, 2020). "Together, these results indicate a possibility that arginine-induced neuroprotective effect may be through the suppression of HIF-1α/LDHA-mediated inflammatory response in microglia after cerebral ischemia injury." (PMID 32321555, 2020). "Similarly, the upregulation of hypoxia-inducible factor 1-alpha (HIF-1α) after cerebral ischemia results in iron overload, increasing transferrin receptor 1 (TFR1) expression." (PMID 32848555, 2020).
Cerebral ischemia (continued). "Moreover, HIF-1α and procaspase-3 showed similar expression pattern following photothrombotic cerebral ischemia." (PMID 30671433, 2018). "TFR1 is upregulated in brain ischemia due to hypoxia-inducible factor 1-alpha (HIF1-α) actions." (PMID 29415739, 2018). "HIF-1α has been recognized as neuroprotective in cerebral ischemia in the past two decades." (PMID 28289375, 2017). "HIF-1α was found to be an important player in cerebral ischemia." (PMID 26030758, 2015). "In this study, we aim to identify the miRNAs that could directly regulate Hif-1a expression and bring about a favorable outcome through the reduction of infarct size in cerebral ischemia." (PMID 26030758, 2015). "Several studies have reported that inhibition of Hif-1α in acute phase could bring about beneficial effect during cerebral ischemia." (PMID 26030758, 2015). "In this study, we aimed to elucidate the interaction between miRNA and Hif-1α in cerebral ischemia." (PMID 26030758, 2015). "While the decrease in Hif-1α expression level is favored for the reduction in infarct volume in the early time of cerebral ischemia (< 24 hrs), an increased expression of Hif-1α proved to be beneficial in the late time (> 24 hrs) of permanent middle cerebral artery occlusion model." (PMID 26030758, 2015). "HIF-1α as a key regulator following cerebral ischemia is activated after SAH." (PMID 25867893, 2015). "However, the implication of modulating the expression of HIF-1α using miRNAs in cerebral ischemia remains unexplored." (PMID 26030758, 2015). "Cerebral ischemia caused by a lack of cerebral perfusion pressure plays a key role in a process that leads from high intracranial venous pressure to increased HIF-1α expression and subsequently increased VEGF expression." (PMID 25160131, 2014). "To test this hypothesis, we studied and compared the cell-type-specific expression of HIF-1α in pyramidal neurons and interneurons in a primary cortical neuronal culture exposed to hypoxia and an animal model of cerebral ischemia." (PMID 24887017, 2014). "In the present study, it has been demonstrated that the treatment of hinokitiol in MCAO-induced embolic rats significantly reduced the expression of HIF-1α and iNOS, harmful to the postischemic brain, and may be of worth in the treatment of cerebral ischemia." (PMID 24285977, 2013). "Moreover, we demonstrated that cerebral ischemia–reperfusion injury (CIRI) promoted mTOR/HIF‐1α signaling pathway expression, which could be further enhanced via the knockdown of SESN2." (PMID 40032632, 2025). "HIF-1α could serve a dual role in cell survival or death during cerebral ischemia/hypoxia." (PMID 39108657, 2024). "Therefore, the present study is aimed at determining whether treatment with ADPN would attenuate cerebral ischemia-reperfusion injury through the increased antioxidant capacity dependent on HIF-1α." (PMID 34336097, 2021). "Increased expression and stabilization of HIF-1α enhance angiogenesis and erythropoiesis, activate anti-apoptotic cascades, and thus can represent a promising therapeutic strategy in the treatment of cerebral ischemia and multiple neurodegenerative disorders, including AD, PD, ALS, and MS." (PMID 34395432, 2021). "HIF1A‐dependent transcriptional regulation is well known to promote hypoxic adaptation, perhaps through an astrocyte‐based mechanism, which could provide compensatory neuroprotection during cerebral ischemia, and by corollary, in AD." (PMID 34117818, 2021). "Though the co-ordinated regulation of all the 3 isoforms of HIF-α maybe contributing to the physiological changes during hypoxia, it appears that it is the activity of HIF-1α isoform possibly conferring neuroprotection or beneficial effects (to the cells) during cerebral ischemia." (PMID 26030758, 2015). "Thus, downregulating Hif-1α expression through miR-335 mimics, in the early time of cerebral ischemia could prove to be useful in reducing infarct volume of the eMCAo model." (PMID 26030758, 2015).
Cerebral ischemia (continued). "In this study, we first reported upregulation of Hif-1α by administration of anti miR-335 in the late time of cerebral ischemia and displayed that induction of anti miR-335 at 24 hrs post-occlusion could upregulate Hif-1α expression and bring about reduction of infarct volume." (PMID 26030758, 2015). "A previous study has illustrated that ischemic preconditioning upregulates HIF-1α level in hippocampal CA1 area, thus inducing VEGF expression and activating NF-κB signaling to protect against cerebral ischemia." (PMID 40653468, 2025). "In summary, the absence of α-Syn alters the expression dynamics of key genes involved in the ischemic response, such as HIF-1α and its downstream target genes (VEGF-A, and VEGFR-1) after brain ischemia." (PMID 40964705, 2025). "We previously confirmed that the expressions of HIF‐1α and VEGF were increased in hippocampal CA1 after transient global cerebral ischemia." (PMID 39072998, 2024). "Our study demonstrated the inhibition of the mitochondrial apoptosis pathway and the upregulation of the HIF-1α/VEGF pathway by Cox7c, resulting in a neuroprotective effect during cerebral ischemia/reperfusion." (PMID 36909178, 2023). "Zinc significantly increased the protein levels of HIF‐1α, VEGF‐A, and VEGF‐R2 in astrocytes, and promoted angiogenesis during cerebral ischemia repair." (PMID 35855611, 2022). "In prolonged cerebral ischemia, the level of prolyl hydroxylase 2 (PHD2) decreases, probably because PHD2 is the transcription target of HIF-1α." (PMID 35265143, 2022). "Celastrol was found to inhibit the upregulation of HIF-1α and PDK1 induced by cerebral ischemia in the I/R + Celastrol group as compared with the I/R group." (PMID 35035665, 2022). "Another study showed that ROS production and protein nitrosylation, iNOS, gp91phox/NADPH oxidase 2 (NOX2), IL-1β, and HIF-1α levels were decreased by ANDRO (5 and 10 μg/kg, i.v.)in cerebral ischemia in rats." (PMID 35154564, 2022). "In summary, our results show that during acute cerebral ischemia, inhibiting NADPH oxidase with apocynin reduced BBB damage by regulating HIF-1α upregulation and MMP-2 induction." (PMID 34434231, 2021). "Hypoxia-inducible factor 1 activator, dimethyloxalylglycine (DMOG), and HIF-1α inhibitor, acriflavine (ACF), were used to evaluate the hypoxia-inducible factor 1 activity during cerebral ischemia." (PMID 34205911, 2021). "Even though HIF-1α has been shown to play a role in TBI progression and cerebral ischemia, few studies have examined its role after mTBI and it has not been investigated in relation to BPT." (PMID 28424745, 2017). "Our results indicate that 20S proteasomes are involved in HIF-1α degradation in ischemic neurons and that proteasomal inhibition provides more HIF-1α stabilization and neuroprotection than PHD inhibition in cerebral ischemia." (PMID 28566998, 2017). "In our study, overexpression of HIF-1α was induced by IRI, while it was markedly attenuated in LRIP group during early cerebral ischemia." (PMID 26715469, 2015). "Moreover, the HIF-1α subunit shows biphasic activation in rat stroke models resulting in expression of apoptosis-related genes during the early chronic phase (8 h after stroke onset) but shifts to protective gene expression during the recovery phase (after 48 h) of cerebral ischemia." (PMID 24961318, 2013). "Quantitative western blot analysis showed that cerebral ischemia induced by transient MCAO triggered a significant (*P<0.05, n = 4) increase in the HIF-1α protein levels in the ischemic hemisphere." (PMID 23094105, 2012).
Cerebral ischemia (continued). "Additionally, EMPA upregulates HIF-1α and VEGF, thereby reducing neuronal apoptosis and improving neurobehavioral outcomes in cerebral ischemia/reperfusion injury." (PMID 41011131, 2025). "We explain this effect from the perspective of its impact on the GSH-dependent pathways of endogenous neuroprotection and the increased expression of mRNA for HSP70, HIF-1α, and HIF-3α under conditions of acute experimental cerebral ischemia, as well as the enhancement of glutathione synthesis." (PMID 40299680, 2025). "In mice lacking α-Syn, the mRNA levels of HIF1α were significantly reduced after brain ischemia, especially at 48 hours after reperfusion, compared with wild-type C57BL/6J mice." (PMID 40964705, 2025). "A study on the mechanism of CAT in cerebral ischemia stated that CAT protected vascular structure and promoted angiogenesis in focal cerebral ischemic rats by activating the hypoxia-inducible factor 1-alpha (HIF-1α)/vascular endothelial growth factor (VEGF) pathway." (PMID 38773376, 2024). "Furthermore, a result indicates that 20S proteasomes are involved in HIF-1α degradation in ischemic neurons and that proteasomal inhibition provides more HIF-1α stabilization and neuroprotection than PHD inhibition in cerebral ischemia." (PMID 35462700, 2022). "Thus, we investigated the effect of zinc on the levels of HIF‐1α, VEGF‐A, and VEGF‐R2 during the cerebral ischemia repair stage." (PMID 35855611, 2022). "Studies have shown that HIF-1α has neuroprotective effects on cerebral ischemia, while others have reported negative effects such as interruption of the blood-brain barrier (BBB) integrity after stroke." (PMID 34966392, 2021). "However, knockdown of HIF-1α partially reversed the antioxidant and treatment effect of ADPN after cerebral ischemia." (PMID 34336097, 2021). "Administration of deferrioxamine (an iron chelator), both in vivo and in vitro, has been found to promote the expression of HIF-1α and EPO, thus improving the tolerance against cerebral ischemia, increasing neuronal viability, and exerting protective effects on OGD-cultured neurons and MCAO rats." (PMID 34966392, 2021). "The results displayed that 2ME2 markedly suppressed the expression of HIF-1α and IRAK-M at 1 h after brain ischemia compared with the vehicle treated group, indicating that the increase of HIF-1α correlates with the upregulation of IRAK-M after cerebrovascular obstruction and reperfusion." (PMID 30622459, 2018). "Here we report that hypoxia-inducible factor-1α (HIF-1α) activation upregulates pituitary adenylate cyclase-activating peptide 38 (PACAP38), which in turn activates PACAP type 1 receptor (PAC1) under hypoxia in vitro and cerebral ischemia in vivo." (PMID 25523790, 2015). "Hypoxia/ischemia-induced PACAP38 upregulation was abolished in neural tissues with decreased HIF-1α activity that resulted from the injection of the HIF-1α-specific inhibitor, 2-ME2; in animals with cerebral ischemia and in a Cre-loxP-based approach to knockout HIF-1α in mice." (PMID 25523790, 2015). "The activation of HIF‐1α/VEGF pathway plays an important part in the regulation of angiogenesis and neuronal survival, whereas the absence of neuronal HIF‐1α inhibited angiogenesis, aggravated neuronal death and impaired neurobehavioral function after focal cerebral ischemia in mice." (PMID 39072998, 2024). "Thus, the observed lack of Tnfα upregulation in our study is not surprising, as we had no increased Hif1α levels and no cerebral ischemia." (PMID 38405120, 2024).